MXD3 (MAX dimerization protein 3)
Diseases named in the same sentence as MXD3 in open-access papers (continued):
Sharing a sentence is not in itself a finding about the gene and the disease.
renal carcinoma (3 papers, 2024 to 2025). A carcinoma arising from the epithelium of the renal parenchyma or the renal pelvis. "Nine intersecting genes were screened and used to construct a prognostic model, whereby seven key biomarkers—MXD3, PLCB2, CCDC88B, DEF6, IFNG, TBC1D10C, and PLEKHN1—were significantly influenced the prognosis of renal cancer." (PMID 41357186, 2025). "The results of the TCGA-KIRC cohort showed that either in paired or unpaired renal cancer tissues, except for CLIC5, which was in a low expression state, the remaining four genes (MXD3, NUF2, PABPC1L, and PLK1) were in a high expression." (PMID 38546385, 2024).
Bladder cancer (2 papers, 2021). "In contrast, higher MXD3 expression was associated with the clinical benefits of PD-L1 in bladder cancer." (PMID 34584637, 2021). "However, increased expression levels of MXD3 in bladder cancer cohorts were negatively associated with the level of CTL, suggesting an interplay with T cell exclusion." (PMID 34584637, 2021). "In contrast, higher MXD3 expression was associated with clinical benefits in bladder cancer patients to PD-L1 ICB and hence exhibited higher survival durations than bladder cancer cohorts that had lower MXD3 expression levels." (PMID 34584637, 2021). "Bladder cancer patients with high MXD3 expression had a better prognosis after treatment with ICIs (p = 0.005)." (PMID 34859046, 2021). "The prognosis of patients with high MXD3 bladder cancer in the GEO database is poor, but the bladder patients in the MXD3 group have better prognosis after treatment with the immunotherapeutic point inhibitor." (PMID 34859046, 2021).
clear cell renal cell carcinoma (2 papers, 2022 to 2024). "Similarly, CLIC5 expression was found to be lower than that of normal kidney tissues in renal clear cell carcinoma tissues extracted from our research center, while MXD3, NUF2, PABPC1L, and PLK1 were significantly higher in renal clear cell carcinoma tissues than in normal kidney tissues." (PMID 38546385, 2024).
liver cancer (2 papers, 2021 to 2025). An epithelial or non-epithelial malignant neoplasm that arises from the liver. "The MXD3 promoter sequence region has a tendency to be hypomethylated in liver cancer in respect to adjacent tissue samples." (PMID 34943942, 2021).
prostate carcinoma (2 papers, 2022 to 2024). A carcinoma that arises from epithelial cells of the prostate gland. "However, the function of MXD3 in prostate cancer requires further investigation." (PMID 36704352, 2022).
B-cell acute lymphoblastic leukemia (1 paper, 2022). A neoplasm of lymphoblasts committed to the B-cell lineage, typically composed of small to medium-sized blast cells. "A preclinical study on precursor B-cell acute lymphoblastic leukemia reported that an anti-CD22 antibody-MXD3 ASO conjugate decreased MXD3 expression by 60% to 70% in different cell lines compared to untreated cells." (PMID 36365206, 2022).
brain cancer (1 paper, 2021). A primary or metastatic malignant neoplasm affecting the brain. "Therefore, MXD3 appears to be associated with cell proliferation and a variety of human brain cancers." (PMID 34584637, 2021).
endometrial cancer (1 paper, 2021). Primary or metastatic malignant neoplasm involving the endometrium (mucous membrane that lines the endometrial cavity). "In contrast, hypomethylation of MXD3 was associated with a good prognosis in endometrial cancer." (PMID 34584637, 2021). "However, our findings indicated that the methylation status of MXD3 mediated dysfunctional T-cell phenotypes and worse prognoses of KIRP and endometrial cancer via a mechanism that differs from other cancer types." (PMID 34584637, 2021).
kidney papillary carcinoma (1 paper, 2021). "In accordance with the differential methylation status of MXD3 in KIRP, hypermethylation in KIRP was positively associated with dysfunctional T-cell phenotypes but was associated with longer survival of kidney papillary carcinoma cohorts." (PMID 34584637, 2021).
osteosarcoma (1 paper, 2021). A usually aggressive malignant bone-forming mesenchymal neoplasm, predominantly affecting adolescents and young adults. "To characterize the intracellular localization of MXD3, we assessed the distribution of MXD3 within the endoplasmic reticulum (ER) and microtubules of PC-3, MCF-7, and U-2 osteosarcoma (OS) cells using an indirect immunofluorescence assay." (PMID 34584637, 2021).
Pca (1 paper, 2022). "Kaplan-Meier analysis of TCGA data indicated that the level of MXD3 expression was significantly associated with RFS of Pca patients." (PMID 36704352, 2022). "For additional exploration of the biological function of MXD3 in PCa, we performed in vitro experiments to validate the oncogenic role of MXD3 in the PC3 PCa cell line." (PMID 36704352, 2022). "Additionally, we analyzed the differential expression level of the MXD3 in various pathological stages and Gleason score of Pca patients using TCGA data; the findings indicated that MXD3 is significantly upregulated in higher T stage and higher Gleason score groups." (PMID 36704352, 2022). "The signature, comprising four genes (MXD3, SSTR1, AMH and PPFIA2), was utilized to classify PCa patients into two risk groups; the high-risk group was characterized by poor prognosis and more aggressive clinical features." (PMID 36704352, 2022). "Cell proliferation was evaluated using the CCK-8 method, and the results suggested that MXD3 knockdown significantly reduced the growth of PCa cell." (PMID 36704352, 2022). "We confirmed that the downregulation of MXD3 significantly suppressed the proliferation of PCa cells in vitro." (PMID 36704352, 2022). "Because MXD3 is a hub gene with a central role in the PCa signature, we focused on MXD3 during in silico and in vitro analyses." (PMID 36704352, 2022). "Collectively, these results demonstrated that MXD3 is essential for growth of PCa cell." (PMID 36704352, 2022). "Furthermore, we found that MXD3 downregulation suppressed the proliferation of PCa cell lines in vitro." (PMID 36704352, 2022). "Analysis of TCGA PCa data revealed that MXD3 was strongly upregulated in PCa tissue." (PMID 36704352, 2022).
tumor (13 papers, 2012 to 2025). "Further research is warranted to elucidate the underlying mechanisms by which methylation affects MXD3 expression and its implications for tumor progression and treatment response in LUSC." (PMID 40406509, 2025). "High MXD3 expression was associated with advanced tumor differentiation grade, larger tumor size, and advanced T and N stages, indicating a potential role of MXD3 in tumor aggressiveness and metastasis." (PMID 40406509, 2025). "Previous studies have shown the association of MXD3 expression levels and genetic or epigenetic alterations with tumour stage, metastasis, TME, immune escape and drug sensitivity in 39 TCGA cancer types and subtypes, including ccRCC." (PMID 38546385, 2024). "For example, the Sonic Hedgehog (Shh) variant of medulloblastoma expresses high levels of Mxd3 and Mycn in the cerebellar granule neuron precursors (GNPs) or nestin-expressing progenitors from which tumor cells are thought to originate." (PMID 35203395, 2022). "In contrast to MXD1 and MXD2, fewer studies have implicated MXD3 in the direct pathogenesis of human cancer and/or tumor suppression." (PMID 35203395, 2022). "For example, 11 of the 14 tumor types (78.6%) expressing the highest levels of Mxd4 are associated with more prolonged survival, whereas in the case of Mxd3 this is true for only 5 of 17 tumor types (29.4%) in the case of Mxd3." (PMID 35203395, 2022). "Our results indicated that MXD3 was aberrantly expressed in almost all The Cancer Genome Atlas (TCGA) cancer types and subtypes and was associated with the tumor stage, metastasis, and worse prognoses of various cohorts." (PMID 34584637, 2021). "However, MXD3 expression exhibited a statistically significant association with tumor differentiation grade (⁣∗p = 0.023), tumor size (⁣∗p = 0.006), T stage (⁣∗p = 0.004), and N stage (⁣∗p < 0.001)." (PMID 40406509, 2025). "Similarly, MXD3 expression was significantly associated with larger tumor size (≥ 3.0 cm) and advanced T and N stages, suggesting a potential role of MXD3 in tumor aggressiveness and metastasis in LUSC." (PMID 40406509, 2025). "Importantly, correlation analysis between risk-related genes and tumor-infiltrating immune cells revealed that MXD3 had the strongest positive correlation with the number of regulatory T-cell." (PMID 36704352, 2022). "The analysis included variables such as tumor size, T stage, N stage, radiotherapy, chemotherapy, and MXD3 expression level." (PMID 40406509, 2025). "In fact, as will be illustrated in the following discussion, our further investigation revealed that MXD3 genetic and epigenetic modifications play a role in the regulation of the tumor immune milieu." (PMID 39287260, 2024). "Analysis of the GSE159115 database showed that five genes in malignant and stromal cells differed significantly between tumour and normal tissues, but only MXD3, NUF2 and PLK1 in immune cells." (PMID 38546385, 2024). "Further experimental studies are, however, required to unravel how MXD3 mediates the involvement of ion homeostasis in tumor development and progression." (PMID 34584637, 2021). "IHC results showed that the nuclear localization of the MXD3 protein was significantly increased in tumor samples compared to normal tissue." (PMID 34859046, 2021). "This study demonstrated the relationships of expression levels and genetic or epigenetic alterations of MXD3 with tumor staging, metastasis, TME, immune evasion, and drug sensitivity across 39 TCGA cancer types and subtypes." (PMID 34584637, 2021). "We then analyzed the infiltration of immune cells in the tumor and combined it with the MXD3 expression level." (PMID 34859046, 2021). "We also verified the differential expression of three clinical phenotypes of MXD3: age, sex, and tumor stage, in a variety of tumors, suggesting a correlation between MXD3 and clinical characteristics." (PMID 34859046, 2021).
tumor (continued). "Using various computational tools, we interrogated the role of MXD3 in tumor immune infiltration, immune evasion, tumor progression, therapy response, and prognosis of cohorts from various cancer types." (PMID 34584637, 2021). "We report patterns of gene expression in MXD3-overexpressing cells, as well as candidate direct target genes, as a first effort to elucidate mechanisms of MXD3 function and its role in tumor cell proliferation and tumorigenesis pathways." (PMID 22808009, 2012). "Notably, MXD3 expression levels were found to correlate with tumor differentiation grade, with higher MXD3 expression observed in poorly differentiated tumors compared to well and moderately differentiated tumors." (PMID 40406509, 2025). "Additionally, high levels of RECQL4, MXD3, and PRR7 mRNA expression are associated with advanced tumor stages." (PMID 35681785, 2022). "Five variables (LINC01089, RGS11, MXD3, BIRC5, and RAB30) of Sig27var25 are risk factors of poor OS and three of them remain risk factors of fatality after adjusting for age at diagnosis and tumor stages." (PMID 35681785, 2022). "Altogether, these findings strongly suggest that MXD3 is an oncogenic molecule of tumor progression, various tumor stages, and metastasis, and hence could serve as early biomarker for cancer detection, staging, and follow-up." (PMID 34584637, 2021). "The differential methylation statuses of MXD3 in TCGA cancers were negatively correlated with differential mRNA overexpression levels in those cancers, suggesting that epigenetic methylation of MXD3 could affect the transcriptome of TCGA tumor cells." (PMID 34584637, 2021). "Our study suggests that 18 types of cancer have higher MXD3 expression in tumor samples." (PMID 34859046, 2021). "These pathways further illustrate the role of MXD3 in carcinogenesis and tumor immunity." (PMID 34859046, 2021). "However, in contrast our further analysis suggested the involvement of MXD3 genetic and epigenetic alterations in regulating the tumor immune microenvironment and worse clinical prognoses of cohorts of those cancers." (PMID 34584637, 2021). "Two main aims in this study were to (i) analyze the role of MXD3 in proliferation of tumor cells and (ii) identify potential target genes and patterns of gene expression induced by this transcription factor as a first approach to understand the molecular mechanisms by which MXD3 exerts its function." (PMID 22808009, 2012). "In conclusion, our results suggest that MXD3 plays pivotal pathogenic roles in the immuno-oncology context of the TME, prognoses, and therapeutic responses through different mechanisms involving T-cell exclusion, tumor infiltration of immune cells in THYM, LICH, and HNSC." (PMID 34584637, 2021). "However, when we compared expression profiles between tumor stages, we found that MXD3 expression increased at higher tumor stages in adrenocortical carcinoma (ACC), KICH, kidney renal clear cell carcinoma (KIRC), kidney renal papillary cell carcinoma, LICH, and SKCM." (PMID 34584637, 2021). "Therefore, we speculated that T-cell exclusion is the major mechanism through which MXD3 regulates tumor escape of immune cells, tumor promotion, and metastasis." (PMID 34584637, 2021). "This study is aimed at addressing this gap by examining the expression and functional implications of MXD3 in LUSC, seeking to elucidate its role in tumor progression and its potential utility as a clinical biomarker." (PMID 40406509, 2025). "To further examine the roles of MXD3 and MXI1 in tumors, we proved that the expression of MXD3 in tumor tissue was higher than that in adjacent tissues, while the expression of MXI1 in tumor tissue was lower than that in adjacent tissues." (PMID 39287260, 2024). "We concluded by comparing MAX dimerization protein 3 (MXD3) and MAX interactor 1 (MXI1) expression in tumor tissues using Uniform Manifold Approximation and Projection and violin plots in the Tumor lmmune Single-cell Hub database." (PMID 39287260, 2024).
tumor (continued). "MXD3 is a transcription factor belonging to the MYC/MAX/MXD transcriptional network, and its expression is increased in tumor tissues." (PMID 34671559, 2021). "To test this hypothesis, we analyze MXD3 expression patterns in LUSC tissue samples and correlate these with clinical and pathological features, including tumor differentiation, stage, and survival data." (PMID 40406509, 2025). "Sig27var25 and SigIQvar8 are highly effective at predicting ACC prognosis and progression; both signatures contain component genes predicting poor OS independently of age and tumor stages, for instance SNHG10 and RECQL4 for SigIQvar8 as well as MXD3, BIRC5, and RAB30 for Sig27var25." (PMID 35681785, 2022). "However, the involvement of tumor infiltration of immune cells in THYM, LICH, and HNSC suggests that MXD3 exhibits a tissue-dependent mechanism of regulating immune evasion." (PMID 34584637, 2021). "We, therefore, postulated the possibility that high MXD3 expression levels in those cancer types are a byproduct of dysregulated signaling without prognostic significance for tumor cells." (PMID 34584637, 2021). "In most of the remaining cancers, the expression of MXD3 was not significantly different between different tumor stages." (PMID 34859046, 2021). "Generally, MXD proteins are functional antagonists of MYC, acting as transcriptional repressors to promote cell differentiation; however, MXD3 is an atypical member that has roles in cell cycle progression and cell proliferation rather than differentiation, thus act as a tumor promoter." (PMID 34584637, 2021).
cancer (12 papers, 2012 to 2025). A tumor composed of atypical neoplastic, often pleomorphic cells that invade other tissues. "Patients with high MXD3 expression levels had over threefold increased risk of cancer-related mortality compared to those with low expression levels, underscoring the robust prognostic significance of MXD3 in LUSC." (PMID 40406509, 2025). "Our survival analyses revealed that high MXD3 expression was significantly associated with shorter overall and cancer-specific survival in LUSC patients." (PMID 40406509, 2025). "The Kaplan–Meier survival analyses revealed that high MXD3 expression was associated with shorter cancer-specific survival." (PMID 40406509, 2025). "In almost all cancers, MXD3 was significantly associated with a variety of apoptosis genes, demonstrating MXD3’s considerable impact on apoptosis." (PMID 34859046, 2021). "In contrast, in our findings, MXD3 was significantly negatively associated with the number of DCs in almost all cancers." (PMID 34859046, 2021). "Our results also suggested that MXD3 expression is associated with immune or chemotherapeutic outcomes in various cancers." (PMID 34584637, 2021). "We analyzed associations between MXD3 expression and activities of different clinical chemotherapies on various cancer cell lines." (PMID 34584637, 2021). "Surprisingly, we found that higher expression levels of MXD3 were associated with decreased sensitivity of cancer cell lines to several MEK inhibitors but led to increased activities of other kinase inhibitors, including Akt inhibitors." (PMID 34584637, 2021). "In all cancers, MXD3 is associated with most apoptosis pathway–related genes, confirming previous reports that MXD3 knockdown can induce apoptosis." (PMID 34859046, 2021). "Altogether, these data extend our knowledge of MXD3 in the context of human cancers while characterizing a previously unstudied splice variant of MXD3." (PMID 30838212, 2019). "We examine the possibility that aberrant regulation of the MXD3 message is the cause of abnormal MXD3 expression across cancers." (PMID 30838212, 2019). "We queried the frequencies and types of genetic alterations of MXD3 across the various cancer types and found that gene amplification was the most frequent genetic alteration of MXD3 followed by MXD3 mutations and deep deletions, while multiple alterations of MXD3 were less frequent." (PMID 34584637, 2021). "MXD3 appears to be linked with various human cancers and adipogenesis." (PMID 34943942, 2021). "In addition, upon further exploration of the critical role of MXD3 in predicting therapeutic responses, we analyzed associations of MXD3 expression with activities of various clinical chemotherapies on cancer cell lines." (PMID 34584637, 2021). "Consequently, we queried the types and genetic alteration frequencies of MXD3 across various cancer types and found that gene amplification and mutations were the most frequent genetic alterations of MXD3, while deep deletions occurred less frequently." (PMID 34584637, 2021). "Methylation of MXD3 was inversely associated with messenger (m)RNA expression levels and mediated dysfunctional T-cell phenotypes and worse prognoses of cohorts from different cancer types." (PMID 34584637, 2021). "In addition, higher MXD3 expression levels were associated with decreased sensitivity of cancer cell lines to several mitogen-activated protein kinase kinase (MEK) inhibitors but led to increased activities of other kinase inhibitors, including Akt inhibitors." (PMID 34584637, 2021). "Similarly, genetic alterations of MXD3 co-occurred with the frequency and pattern of genetic alterations of these same genes, suggesting that these genes are functional partners associated with the oncogenic role of MXD3 in various cancer types." (PMID 34584637, 2021). "Multivariate Cox regression identified MXD3 expression level and lymph node involvement (N stage) as independent prognostic factors for cancer-specific survival in LUSC patients." (PMID 40406509, 2025).